MIR600 (microRNA 600)
Synonyms: hsa-mir-600; MIRN600
Gene: MicroRNA gene on chromosome 9 (123,111,546 to 123,111,643, reverse strand). Ensembl gene ENSG00000283941.
Gene Ontology:
Biological process: miRNA-mediated post-transcriptional gene silencing
Cellular component: RISC complex
Homologues: Orthologues: chimpanzee ptr-mir-600 (100% identical), macaque mml-mir-600 (92% identical).